GATA3 (GATA binding protein 3)
Diseases named in the same sentence as GATA3 in open-access papers (continued):
Sharing a sentence is not in itself a finding about the gene and the disease.
lymph node metastasis (17 papers, 2013 to 2025). "There were associations between GATA-3 (p < 0.001), Ki-67 (p = 0.003), tumor size (p < 0.001), clinical stage (p = 0.002), lymph node metastasis (p < 0.001), and histological grade (p < 0.001) by univariate survival analysis." (PMID 37483298, 2023). "The association of GATA3 positivity with patients’ gender, tumour stage, grade, histology and the presence of lymph node metastasis was evaluated in a binary meta-analysis." (PMID 34690921, 2021). "Looking at clinico-pathological parameters, based on our findings, GATA3 positivity is inversely associated with the most important clinical prognostic factors of BC outcome, namely tumor size and lymph node metastasis." (PMID 33800667, 2021). "Contradictorily, individual studies found significant correlation between increased GATA3-positivity and cases with lymph node metastasis while in another data set it was associated with lymph node negative cases." (PMID 34690921, 2021). "All data indicate that Notch3 expression positively correlates with elevated expression of GATA-3, ER and PR, as well as with a lower risk of lymph node metastasis." (PMID 30100605, 2018). "Here, low GATA3 mRNA is associated with lymph node metastasis (p ≤ 0.003)." (PMID 41024411, 2025). "At the N0 and N1 phases of lymph node metastasis, we noticed that GATA3 mRNA expression levels in KIRC tissues were lower than those in normal tissues." (PMID 36961416, 2023). "High GATA3 expression significantly correlated with adverse prognostic factors including lymph node metastasis, distant metastasis, high grade, perineural invasion, lymphovascular invasion, extracapsular spread and presence of locoregional recurrence." (PMID 28263977, 2017). "In contrast, patients without lymph node metastasis were found to have more frequent mutation in four genes including GATA3, FOXA1, ANKRD11, and RET (P<0.05) and more CN amplifications in two genes including PIK3C2G and CCND2 (P<0.05)." (PMID 33968723, 2021). "Nevertheless, we noted that the luminal differentiation factor GATA3 was expressed at relatively high levels both in PM and in PNM samples, as well as in matched lymph node metastases." (PMID 24205108, 2013). "In addition to the GATA3/FOXA1 combination expression, tumor grade, pT stage, lympho-vascular involvement, lymph node metastasis, and extensive necrosis all contributed to DFS and CSS in the univariate analysis." (PMID 38425344, 2024). "The lymph node metastasis rate was not significantly different between GATA3-positive and -negative UCs (0.375, 95% CI: 0.282−0.478 vs. 0.340, 95% CI: 0.239−0.459)." (PMID 37629741, 2023). "In our study, the lymph node metastasis rate was not significantly different between GATA3-positive and -negative UCs." (PMID 37629741, 2023). "In particular, the subanalysis also revealed that an elevated GATA3 mRNA expression was related to a longer RFS time in the PR-positive patients (patients = 589, HR = 0.67, 95% CI: 0.47–0.95, p = 0.025) and the w/o lymph node metastasis group." (PMID 30872657, 2019). "Our data show that GATA3 expression is upregulated in HNSCC and high GATA3 expression correlates with lymph node metastasis, distant metastasis, high grade, presence of perineural invasion, lymphovascular invasion, nodular extracapsular spreads and locoregional recurrence." (PMID 28263977, 2017). "Model A (without containing GATA3 expression) confirmed age (P = 0.003), depth of tumor infiltration (P<0.001), lymph node metastasis (P<0.001), and distant metastasis (P<0.001) as independent predictors of the overall survival of patients with gastric adenocarcinoma." (PMID 24504018, 2014). "Moreover, we found that Notch3 and/or GATA-3 negative patients exhibited more lymph node metastases; this implies that the absence or low expression of Notch3/GATA-3 may indicate a high potential for metastasis." (PMID 30100605, 2018).
lymph node metastasis (continued). "In consistent with above findings, we also found that low GATA3 mRNA predicted poor DMFS for patients with or without lymph node metastasis and that high FOSL1 predicted a poor outcome for patients with no lymph node metastasis." (PMID 37353480, 2023).
Obesity (17 papers, 2016 to 2026). Accumulation of substantial excess body fat. "GATA3 is a well-known transcription factor for T cells, the expression of which is positively associated with visceral obesity, obesity-related inflammation, and insulin resistance." (PMID 40529363, 2025). "Consistent with this, the suppression of GATA3 has been shown to improve the adipogenesis process, restore insulin sensitivity, and reduce obesity-associated inflammation in patients with obesity." (PMID 40423250, 2025). "RPS6KB1 (an AMPK responsive gene for protein synthesis and cell growth), estrogen receptor α (encoded by the ESR1 gene) and its target gene GATA3, were significantly downregulated in rFNAs from premenopausal women with obesity." (PMID 34485137, 2021). "High-dose hgd40 reduced hepatocyte ballooning degeneration, but caused a borderline increase in fatty changes, suggesting a dual role of GATA-3 in obesity-related liver injury." (PMID 41514930, 2025). "GATA3 upregulation in the VAT of subjects with obesity increased IL-6 secretion, which in turn activated macrophage infiltration by upregulating monocyte chemoattractant protein-1 (MCP-1, encoded by the CCL2 gene)." (PMID 40423250, 2025). "GATA3 is predominantly expressed in preadipocytes, and its upregulation in obesity hinders the ability of the adipose tissue to recruit new fat cells, resulting in ectopic fat deposition." (PMID 40423250, 2025). "Yet, differences from studies in lean mice and the possibility of GATA-3’s dual role underscore the complexity of obesity models and the need for more detailed studies." (PMID 41514930, 2025). "The higher transcription of mRNA FOXP3 and IL-10 (Treg markers), accompanied by a high transcription of TBX21 and IFNG (Th1 markers), GATA3 and IL-4 (Th2 markers) indicated the inflammatory status in the group with obesity and an altered Treg function." (PMID 37215211, 2023). "This is consistent with Gata3-expressing ILC2s, which are reduced with obesity and produce IL33 – a type 2 cytokine that promotes glucose tolerance in mice and is the primary ligand for ST249." (PMID 35618862, 2022). "The expression of GATA3, miR-452, and miR-4713 was also significantly lower in the obesity and the obesity with fracture groups when compared to the NC group." (PMID 35401881, 2022). "In our clinical samples, the expression of GATA3 was significantly lower in the obesity group and the obesity with fracture group compared to the NC group." (PMID 35401881, 2022). "Yet, to investigate whether GATA-3 suppression can affect fat distribution during the accumulation phase of fat depots, a diet-induced obesity model can be used as obesity can be induced by a high-fat diet during the experimental period." (PMID 41514930, 2025). "Multiple earlier reports have pinpointed the role of GATA3 in obesity-related conditions that involve IR, whether left untreated or leading to the incidence of T2D." (PMID 39768217, 2024). "Targeted therapies for obesity and insulin resistance (IR) have been speculated based on outcomes of silencing GATA3 via specific DNAzyme, which induces adipogenesis in 3T3-L1 mouse pre-adipocytes." (PMID 39768217, 2024). "Therefore, GATA3 implementation enhances adipogenesis, modifies fat distribution, improves insulin sensitivity, and reduces obesity-related inflammation, supporting its therapeutic relevance in type 2 diabetes (T2D) pathology." (PMID 39768217, 2024). "GATA3’s impact on metabolic disorders is being evaluated as well, particularly for adipogenesis and insulin sensitivity, which potentiates novel therapies for obesity and type 2 diabetes." (PMID 39768217, 2024). "Similar to previous findings, our study found that GATA3 was a core transcription factor associated with NPY1R expression and was significantly negatively associated with high NPY1R expression in patients with obesity." (PMID 35401881, 2022).
Obesity (continued). "Consequently, defective GATA2 and GATA3 expression is associated with obesity, while expression of GATA2 and GATA3 inhibits adipogenesis and traps cells at the preadipocyte stage, which could be as a result of direct suppression of PPARγ." (PMID 26797605, 2016). "The upregulation of GATA3 in VAT and SAT of individuals with obesity is positively correlated with impaired adipogenesis." (PMID 40423250, 2025). "In this context, we suggest that although the association of overweight/obesity with the analyzed risk homozygous genotypes is clear, it should not be excluded that the genotype of GATA3 variants may partly influence metabolic alterations leading to abnormal nutritional status." (PMID 40421094, 2025). "Meanwhile, studies have shown that inhibiting GATA3 in adipocytes can significantly inhibit adipose differentiation and improve insulin resistance and T2DM induced by obesity." (PMID 38893431, 2024). "So far, our data position GATA3 between the ER stress pathway and TRIP-Br2 to regulate adipose tissues, particularly the inflammatory response during obesity." (PMID 27109496, 2016). "In support of this, obesity studies have suggested GATA3 as a negative transcriptional regulator of adipogenesis." (PMID 41024411, 2025). "In the context of gestational diabetes with obesity and multiple background of recurrent abortion, Th1 transcriptional factor and cytokines are upregulated while GATA3 and IL-4 (belonging to the Th2 phenotype) are not altered in diabetic mothers and their newborns." (PMID 30539027, 2018). "In addition, we also observed that physiological stress induced by HFD- or genetic-induced obesity similarly upregulated Gata3 expression in gWAT and mature gWAT adipocytes but not in iWAT and iWAT SVF." (PMID 27109496, 2016).
ovarian carcinoma (17 papers, 2016 to 2025). A malignant neoplasm originating from the surface ovarian epithelium. "GATA3, which has been associated with tumor progression in ovarian cancer, was also increased." (PMID 35692807, 2022). "GATA binding protein 3 (GATA3) is a transcription factor that is transported into ovarian cancer cells through EVs and increases the expression of CD24." (PMID 39802952, 2024). "Based on the results of this study, GATA3 expression was observed in 18% of endocervical, 7% of endometrial, and 10% of ovarian carcinomas, including 7% of serous and 13% of clear cell carcinomas, often with low intensity (H score<50)." (PMID 39118796, 2024). "Of ovarian carcinomas, 6%, including 2 clear cell carcinomas, 2 mucinous adenocarcinomas, and 2 high-grade serous carcinomas, also showed GATA3 expression." (PMID 39118796, 2024). "A total of 187 samples from different types of endometrial, endocervical, and ovarian carcinomas were analyzed for intensity and percentage of GATA3 expression in tumor cells." (PMID 39118796, 2024). "Overall, GATA3 showed a weak to moderate localized expression in a series of endometrial and ovarian carcinomas." (PMID 39118796, 2024). "GATA2 expression was assessed by Western blotting and qRT-PCR in the ovarian cancer isogenic cell line pair, A2780 and A2780cis, and GATA3 expression in the isogenic PEO1 and PEO4 pair of cell lines, cultured in 0.5% hypoxia." (PMID 32850359, 2020). "TAMs increase the ovarian cancer tumor growth via secreting developmental transcription factors including GATA binding protein-3 (GATA-3) through exosomes." (PMID 32992449, 2020). "However, these markers are not entirely specific, e.g., estrogen receptor can be expressed in ovarian cancer and GATA-3 is also a sensitive marker for urothelial cancer." (PMID 27337944, 2016). "In ovarian cancer, TAMs can release extracellular vesicles (EVs), in which the expression of GATA-binding protein 3 (GATA3) is highly upregulated within the EVs and is transferred into ovarian cancer cells." (PMID 40486886, 2025). "This study was aimed to explore the role of non-structure maintenance of chromosomes condensin I complex subunit H (NCAPH) in the progression of ovarian cancer (OC) and the transcription regulatory effects of GATA binding protein 3 (GATA3) on this gene." (PMID 34399777, 2021). "A study in ovarian cancer might offer valuable insights for us, as it revealed that EVs derived from TAMs encapsulate GATA-binding protein-3 (GATA3), which promotes chemotherapy resistance in ovarian cancer cells to DDP by upregulating the CD24/Siglec-10 axis." (PMID 38816455, 2024). "IRF4, GATA4, GATA3, CIITA, and MYH11 were involved in the immune regulatory network, indicating that these five transcription factors might play a role in the immune microenvironment of ovarian cancer." (PMID 34109184, 2021).
squamous cell carcinoma (17 papers, 2008 to 2025). A carcinoma arising from squamous epithelial cells. "Clinical course, radiologic findings, and immunohistochemistry characteristics, including positive p63, GATA3, and cytokeratin, supported urothelial origin with squamous differentiation over squamous cell carcinoma of the skin." (PMID 38939258, 2024). "P19, diagnosed with stage IIB squamous cell carcinoma, exhibited initial expression of GATA3, PanCK, and HER2." (PMID 36768623, 2023). "Of these, adenocarcinoma, small-cell neuroendocrine carcinoma, and squamous cell carcinoma have GATA3 expression levels of less than 20%." (PMID 37629741, 2023). "Cancer type-specific molecular expression was observed in these three cases, with marked expression of HER2 in endocervical adenocarcinoma and GATA3 in squamous cell carcinoma." (PMID 36768623, 2023). "On the other hand, immunopathological examination of the squamous cell carcinoma on the tongue showed GATA3(−)." (PMID 35078521, 2022). "The small intestinal region was p40-positive GATA3-negative CAM5.2-negative squamous cell carcinoma while peritoneal nodule was GATA3-positive CAM5.2-positive p40-negative adenocarcinoma, suggesting the presence of two independent cancers occurring simultaneously at different organs." (PMID 39516338, 2023). "P18 (squamous cell carcinoma) demonstrated persistent expression of CD13 and mild expression of GATA3/PanCK at the second follow-up, which corresponded to avid uptake in the neck lymph node and histological confirmation of metastasis." (PMID 36768623, 2023). "Both the diseases usually lack expression of ER, PgR, and HER2, and GATA3 may be expressed in both MBC and squamous cell carcinomas." (PMID 40230815, 2025). "GATA3 can be used to distinguish pure UCs and UCs with squamous differentiation from primary squamous cell carcinomas, although these tumors do not always display reactivity to individual markers corresponding to morphologic differentiation." (PMID 38939258, 2024). "A squamous cell carcinoma marker, p40, was highly expressed in the small intestinal lesion but not in the peritoneal lesion, while GATA3 and CAM5.2 were only expressed in the peritoneal lesion." (PMID 39516338, 2023). "Since some squamous cell carcinomas and normal epidermal cells are positive for GATA3, GATA3 is not useful to distinguish primary EMPD from pagetoid squamous cell carcinoma in situ." (PMID 28693610, 2017).
acute lymphoblastic leukemia (16 papers, 2015 to 2025). Leukemia with an acute onset, characterized by the presence of lymphoblasts in the bone marrow and the peripheral blood. "Researchers found that GATA3 polymorphism is significantly associated with the susceptibility of pediatric B-lineage acute lymphoblastic leukemia." (PMID 30044774, 2018). "Genome-wide association studies have reported an association of the GATA3 rs3824662 polymorphism (T allele) with childhood acute lymphoblastic leukemia as well as in adolescents and young adults." (PMID 30044774, 2018). "Two studies recently described the association of two SNPs in the GATA3 locus with susceptibility, development and prognosis of acute lymphoblastic leukemia." (PMID 28881727, 2017). "As aberrant GATA3 mRNA expression has been linked to cancerogenesis, we investigated the role of GATA3 in early T cell precursor acute lymphoblastic leukemia (ETP-ALL)." (PMID 27658391, 2016). "Recent research has identified noncoding genetic variations in GATA3 that increase the risk of acute lymphoblastic leukemia (ALL)." (PMID 39768217, 2024). "GATA3 polymorphisms were reported to be significantly associated with susceptibility of pediatric B-lineage acute lymphoblastic leukemia (ALL), by impacting on GATA3 expression." (PMID 28415601, 2017). "In childhood B cell precursor acute lymphoblastic leukemia (BCP-ALL), specific germline variants of GATA3 were associated with a higher incidence of BCP-ALL and a higher risk of relapse." (PMID 27658391, 2016). "Notably, it has been shown that GATA3 could promote leukemic transformation by driving MYC enhancer activity, and inherited GATA3 variants are associated with Ph-like childhood acute lymphoblastic leukemia and risk of relapse." (PMID 34980123, 2022). "By conducting genome-wide association studies (GWASs), we and other independent groups identified multiple top inherited predispositions to acute lymphoblastic leukemia (ALL) susceptibility, including single nucleotide polymorphisms (SNPs) at ARID5B, IKZF1, GATA3 and etc.." (PMID 33193587, 2020). "In addition, whole genome sequencing of patients with early T-cell precursor acute lymphoblastic leukaemia (ETP-ALL), an aggressive subtype of T-ALL, has revealed GATA3 inactivating lesions disrupting haematopoietic development." (PMID 30463912, 2018). "A recent study on T-cell acute lymphoblastic leukemia (T-ALL) reported that GATA3-driven nucleosome eviction dynamically modulates NOTCH1-MYC enhancer activity and is strictly required for NOTCH1-induced T-ALL initiation and maintenance." (PMID 33918793, 2021). "In T‐cell acute lymphoblastic leukemia (T‐ALL), specific non‐coding mutations upstream of the TAL1 oncogene are capable of generating a self‐sustaining transcriptional loop, which involves several T‐ALL transcription factors such as MYB, GATA3, RUNX1 and TAL1 itself." (PMID 27756687, 2017).